TSPY1 (testis specific protein Y-linked 1)
Description:
May be involved in sperm differentiation and proliferation.
Synonyms: CT78; TSPY; DYS14; pJA923
Tractability: PROTAC: ubiquitination databases record sites on it.
Gene: Protein-coding gene on chromosome Y (9,466,955 to 9,469,749, forward strand). Ensembl gene ENSG00000258992.
Subcellular location: Cytoplasm; Nucleus
Subcellular location (Human Protein Atlas): Cytosol
Gene Ontology:
Molecular function: protein binding
Biological process: sex differentiation; nucleosome assembly
Cellular component: chromatin; cytoplasm; nucleus
Homologues: Orthologues: macaque TSPY2 (71% identical), zebrafish tspy (28% identical), Drosophila melanogaster Set (22% identical), Caenorhabditis elegans spr-2 (19% identical), Drosophila melanogaster Nap1 (15% identical), Caenorhabditis elegans nap-1 (14% identical), Drosophila melanogaster CG3708 (12% identical), Drosophila melanogaster mil (12% identical), zebrafish nap1l4a (12% identical). Paralogues in human: TSPY10 (99% identical), TSPY3 (99% identical), TSPY4 (99% identical), TSPY9 (99% identical), TSPY2 (99% identical), TSPY8 (99% identical), TSPYL1 (34% identical), TSPYL4 (31% identical), TSPYL5 (31% identical), TSPYL2 (30% identical), TSPYL6 (28% identical), SET (26% identical), and 6 more.
Diseases named in the same sentence as TSPY1 in open-access papers:
TSPY1 is named in the same sentence as 36 diseases in open-access papers, as found by Europe PMC text mining. Sharing a sentence is not in itself a finding about the gene and the disease. The quoted sentences say what the papers report.
gonadoblastoma (25 papers, 2006 to 2025). A mixed germ cell/sex cord-stromal tumor characterized by the presence of large germ cells which resemble seminoma cells and small cells which resemble Sertoli or granulosa cells. "The final GO category of genes (GOFMID:0007506) showing loss of methylation consists largely of the TSPY gene family (TSPY1-4, 8 and 10) located on the Y chromosome and thought to be implicated in both normal gonadal development and in gonadoblastoma." (PMID 29598829, 2018). "Moreover, the accumulation of OCT3/4-positive germ cells and loss of expression of TSPY1 has been observed by immunohistochemistry in the progression from gonadoblastoma to invasive germ cell tumors in dysgenetic gonads." (PMID 38337479, 2024). "The TSPY1 gene is located within the gonadoblastoma locus on the Y chromosome (GBY), and in women presenting abnormal karyotypes the TSPY1 gene is thought to play a major role in gonadoblastoma tumorigenesis." (PMID 26335491, 2015). "Lauren demonstrated that TSPY1 presented in most gonadoblastomas using interphase fluorescent in situ hybridization assay." (PMID 24586606, 2014). "TSPY1 is a member of the TSPY/SET/NAP1 superfamily mapped to the critical region harboring the gonadoblastoma locus which was the only oncogenic on the male-specific Y chromosome (GBY)." (PMID 24586606, 2014). "TSPY1 is known as a putative gene for the gonadoblastoma locus on the Y (GBY) chromosome and is abundantly expressed in early stages of tumorigenesis in gonadoblastoma." (PMID 24710048, 2010). "TSPY1 was originally described as the putative gene for the gonadoblastoma locus on the Y (GBY) chromosome." (PMID 24710048, 2010). "Moreover, TSPY1 is abundantly expressed in gonadoblastoma, but it may cease after the transformation of germinal cells into malignant germinoma." (PMID 38337479, 2024).
prostate carcinoma (13 papers, 2006 to 2025). A carcinoma that arises from epithelial cells of the prostate gland. "Multiple CT‐X antigens (e.g., MAGEA, CT1; GAGE, CT4; NY‐ESO‐1, CT6; PAGE, CT16; and TSPY1, CT78) are highly expressed in prostate cancer accompanied by DNA demethylation, and changes in DNA methylation status are associated with tumor metastasis." (PMID 38896069, 2024).
germ cell tumor (10 papers, 2006 to 2024). A benign or malignant, gonadal or extragonadal neoplasm that originates from germ cells. "In complete gonadal dysgenesis, the presence of TSPY1 is associated with a higher risk of gonadal germ cell tumors." (PMID 38337479, 2024).
melanoma (9 papers, 2005 to 2018). A malignant, usually aggressive tumor composed of atypical, neoplastic melanocytes. "TSPY1 contains a putative CpG island in its promoter that is hypermethylated in melanoma cell lines; treatment with 5-aza-dC can restore TSPY1 expression." (PMID 16854234, 2006).
male infertility (6 papers, 2010 to 2023). The inability of the male to effect fertilization of an ovum after a specified period of unprotected intercourse. "Summary of case-control studies dealing with the role of TSPY1 copy number in male infertility." (PMID 24710048, 2010).
carcinoma in situ (4 papers, 2010 to 2019). "In the testis, TSPY1 has also been reported to be highly expressed in carcinoma in situ (CIS) and seminomas and was found to be co-expressed with several germ cell tumor markers." (PMID 24710048, 2010).
Infertility (4 papers, 2010 to 2025). "TSPY1 (Testis-specific protein, Y-linked 1) copy number variation impacts on spermatogenetic efficiency and low copy numbers have been associated with infertility in males." (PMID 26335491, 2015). "Another piece of evidence for a significant contribution of TSPY1 gene dosage to spermatogenesis is the clear positive correlation observed between sperm count and TSPY1 copy number both in the infertile and normozoospermic group." (PMID 24710048, 2010). "In fact, in this study infertile men with abnormal sperm parameters showed a significantly lower number of TSPY1 copies in respect to men with normozoospermia." (PMID 24710048, 2010). "Moreover, this trend toward lower TSPY1 copy number in the infertile group was observed within each Y haplogroup, suggesting that the contraction or expansion responsible for the observed differences between cases and controls occurs in all Y lineages." (PMID 24710048, 2010).
lung adenocarcinoma (1 paper, 2022). A carcinoma that arises from the lung and is characterized by the presence of malignant glandular epithelial cells. "For the third pair of networks, it was demonstrated that the testis-specific protein Y-linked 1 (TSPY1) activates the PI3K/AKT and RAS signaling pathways by suppressing IGFBP3 expression in lung adenocarcinoma and liver hepatocellular carcinoma progression." (PMID 35529499, 2022).
Swyer syndrome (1 paper, 2024). "In Swyer syndrome, the function of the TSPY1 gene is preserved." (PMID 38337479, 2024).
tumor (23 papers, 2005 to 2025). "Recently, the testis-specific protein Y-encoded 1 (TSPY1) has been identified as an antigen that accelerates tumor growth." (PMID 36261201, 2022). "However, mechanisms of TSPY1 how to influence tumor metastasis are still unclear." (PMID 24586606, 2014). "To determine the molecular basis of how TSPY1 enhanced invasive abilities of HCC cells, we next examined two invasion-related genes CXC chemokine receptor 4 (CXCR4) and hypoxia inducible factor-1 (HIF-1) that are known to play major role in tumor metastasis." (PMID 24586606, 2014).
cancer (17 papers, 2005 to 2025). A tumor composed of atypical neoplastic, often pleomorphic cells that invade other tissues. "Research is ongoing to investigate the molecular mechanisms of the functions of the cancer/testis protein encoded by the TSPY1 gene." (PMID 29748603, 2018). "COL27A1, PRUNE2, MAEA, TBC1D3, GADD45B, ANXA8 and TSPY1 have been confirmed to play a pro‐resistant role in various cancers, which reflects the reliability of the hGeCKO library screening to some extent." (PMID 39550701, 2024). "Several CTAs of our panel, such as the MAGE-family members, CTAG1B, TSPY1, and CAGE1, are functionally involved in tumorigeneses and cancer progression by modulating gene expression, regulating mitosis, and tumorigenic signaling." (PMID 34065388, 2021).
TSPY1 also shares sentences with these, for which no sentence is quoted: liver cancer (6 papers); hepatocellular carcinoma (5); prostatic tumor (4); Azoospermia (3); Alzheimer disease (2); dysgerminoma (2); spermatogenic failure (2); testicular germ cell tumours (2); adenocarcinoma (1); amelogenesis imperfecta (1); benign prostatic hyperplasia (1); cervical carcinoma (1); Cirrhosis (1); fibrosis (1); liver disease (1); lung carcinoma (1); malignant germ cell tumor (1); malignant ovarian germ cell tumors (1); neurologic disease (1); ovarian small cell carcinoma (1); pituitary adenomas (1); pituitary tumor (1); seminoma (1); testicular seminoma (1); testicular tumor (1).